ALB (albumin)
Diseases named in the same sentence as ALB in open-access papers (continued):
Sharing a sentence is not in itself a finding about the gene and the disease.
anemia (continued). "We identified six independent predictors that age, pack years, N-stage, LNR, anemia and albumin, were extraordinarily frequent reported prognostic predictors in patients with LSCC." (PMID 32744320, 2020). "In the nomogram, ALT was the largest predictor for KD (100 points), followed by WBC (96 points), PCT (57 points), CRP (53 points), and albumin (58 points), while anemia was the smallest predictor (40 points)." (PMID 32792679, 2020). "A low level of albumin increased markers of thrombosis as well as changes in protein related to anemia and decreased the levels of creatinine and cholesterol." (PMID 33352627, 2020). "Taken together, the level of ALB and the severity of anemia, alongside with other factors, should be taken into account in the selection of blood glucose monitoring method for AA patients with T2DM." (PMID 32352504, 2020). "As for ESRD patients, anemia and serum albumin and parathyroid hormone level had been demonstrated to be associated with CI (Herrmann, Safran, Levkoff, & Minaker, 1992; Stivelman, 2000), which is similar to our study." (PMID 31985179, 2020). "First, a logistic univariate regression analysis was performed, and the results showed that age, anemia, decreased serum albumin level, elevated serum CRP levels, and summer were independent risk factors for peritonitis (p < 0.05)." (PMID 32781861, 2020). "Treatment with chemotherapeutics such as gemcitabine, FOLFIRINOX, and nanoparticle albumin-bound paclitaxel (nAb-PTX) have been reported to induce severe side effects including anemia, depilation, diarrhea, and vomiting in almost all patients." (PMID 31979216, 2020). "Anemia, decreased activated partial thromboplastin time, calcium, and albumin, and increased D-dimer and interleukin-6 were more frequent in severe disease." (PMID 32582740, 2020). "Individuals who had early recovery from anemia also exhibited higher neutrophil counts and albumin levels." (PMID 33072136, 2020). "A direct multivariable logistic regression analysis was performed on OACs prescription at discharge as outcome and five predictors: severe frailty, albumin < 35 g/L, anemia, HAS-BLED score ≥ 3, CHA2DS2-VASc total score." (PMID 31471772, 2020). "Based on the main criterion used to characterize undernutrition (albumin <38 g/l), our results show that 77.27% of the dead patients were malnourished, 81.81% had anemia, 63.63% suffered from hypercholesterolemia, and 13.63% were diabetic." (PMID 31448023, 2019). "The results also revealed that Killip class > 1, anaemia, albumin, uric acid, number of stents and left ventricular ejection fraction (LVEF) were independent predictors of MACCEs in STEMI patients after PCI (all P < 0.05)." (PMID 31722708, 2019). "Anemia was correlated positively with changes in the BMI z-score, body weight, and serum albumin and cholesterol levels, but correlated negatively with serum calcium, iPTH, ferritin levels, and transferrin saturation." (PMID 30700016, 2019). "Risk factors included disturbed renal function and albuminuria (anemia was present in 52% of patients with macroalbuminuria, 24% with microalbuminuria, and only <8% of individuals with normal albumin secretion)." (PMID 29955615, 2018). "In conclusion, these results demonstrate that patients who present with TTS on admission with hypotension, anemia, low albumin levels, elevated lactic acid and renal dysfunction appear to be at higher risk for in-hospital mortality." (PMID 33655139, 2018). "In univariate analysis, factors independently associated with worse PFS were Eastern Cooperative Oncology Group performance status ≥2, Ann Arbor stage III or IV, anemia with Hb levels of <10 g/dL, and serum albumin of <3.5 g/dL." (PMID 29589833, 2018). "Patients who present with TTS and hypotension, anemia, low albumin levels, elevated lactic acid and renal dysfunction were associated with higher rates of in-hospital mortality in this study’s sample population." (PMID 33655139, 2018).
anemia (continued). "Previous studies have shown that, in pregnancy, ESR levels are dependent on gestational age, anaemia, low albumin, other pregnancy complications." (PMID 29686267, 2018). "It consists of nine items: mobility, pressureequipment, anemia, pyrexia, peripheral perfusion, nutrition, serum albumin, weightand incontinence." (PMID 30110107, 2018). "These included variables such as young age, male sex, African-American ethnicity, DM, HTN, obesity, urine protein, serum albumin, anemia, lipidemia, smoking, and cardiovascular disease." (PMID 30286208, 2018). "The positive association between the ERIand CRP values and index reduction with increased albumin are conditions that areclassically described as limitations of anemia treatment with ESAs." (PMID 29742267, 2018). "Biomarkers included nutritional anemia, and serum levels of albumin, cholesterol, magnesium, and glucose." (PMID 29806859, 2018). "Nonetheless, our population showed evidences of significant malnourishment, as indicated by anemia, low albumin level, as well as poor DXA profile (low body fat percentage and BMD)." (PMID 30240396, 2018). "Here, Cox modeling revealed that chronological age, smoking status, some laboratory values (white blood cell count, anemia and albumin), various disease diagnoses as well as body mass index (BMI) and physical fitness were predictive." (PMID 28422991, 2017). "Using principal component analysis (PCA) of the variables they revealed a strong role of markers of anemia and inflammation, which together with calcium und albumin dominated the first PCA axis, while the second axis was related to metabolic syndrome." (PMID 28422991, 2017). "Age, underweight, deficiencies of prealbumin, albumin and iron, and Pf and HIV infections were factors independently associated with anaemia." (PMID 28241813, 2017). "Anemia, low albumin level, leukocytosis and high ESR level are particularly observed in advanced stage disease." (PMID 28291005, 2017). "This study shows that, despite the presence of systemic inflammation, oral supplementation with EAAs can normalise serum albumin in the majority of hypoAlb patients and reverse anaemia in more than one third of subjects after HF." (PMID 28635634, 2017). "Nutritional markers including albumin and total cholesterol were related with a lower prevalence of anemia, which is similar to that of Mn." (PMID 29077007, 2017). "Women were tested for HIV, hepatitis B, syphilis, and bacterial vaginosis along with random blood sugar, urine albumin, and anemia." (PMID 28264668, 2017). "Wound class (p = 0.009), anaemia (p = 0.024), low serum albumin (p = 0.046), and property of suture material used (p = 0.006) were significantly associated with SSIs." (PMID 28168215, 2017). "In this research, wound class, anaemia, low serum albumin, and property of suture material used were significantly associated with surgical site infection." (PMID 28168215, 2017). "In our analysis, anemia, inflammation and albumin were represented by red blood cell counts, fibrinogen, and the albumin/creatinine ratio, respectively." (PMID 28422991, 2017). "Parameters independently associated with anemia parameters in hemodialysis patients were TSAT, ferritin, and albumin." (PMID 28747155, 2017). "It cannot be overlooked that there are also a number of metabolic disturbances present in many cachectic patients such as: glucose intolerance, anemia, and low levels of plasma albumin, most of them included in CASCO." (PMID 28261113, 2017). "Other less common laboratory findings in AOSD include serum albumin < 3.5 gms/dL, anemia of chronic disease, and elevated hepatic transaminase levels." (PMID 27042373, 2016). "We demonstrated a strong and independent association between lower circulating leptin levels and low BMI, anemia, and reduced albumin levels in CKD patients." (PMID 27307101, 2016).
anemia (continued). "Rapid urine LAM testing was more sensitive at diagnosing TB in patients with more advanced disease, as suggested by presence of severe anemia, lower albumin levels, higher acute phase reactants, and a poorer functional state." (PMID 26865526, 2016). "Positive FCAL was associated with colonoscopy findings of active IBD (P < 0.05), low albumin (P < 0.05), anemia (P < 0.01), and elevated CRP (P < 0.01)." (PMID 27774443, 2016). "Several studies have suggested that anemia and the hemoglobin level are related to an increased BMI, a low activity level, an increased age, a low albumin level, a high creatinine level, stroke, gastric ulcers, low triglycerides, and malignant disease." (PMID 27812118, 2016). "The present longitudinal study aimed to determine the relationship between low baseline serum albumin and future development of anemia." (PMID 26644884, 2015). "Typically there are also laboratory abnormalities: hypergammaglobulinemia, elevated inflammatory parameters, anemia, thrombocytosis, leucopenia, low serum albumin level, and, sometimes, elevated interleukin-6 (IL-6)." (PMID 25737793, 2015). "At endpoint, prevalence of anemia in high albumin group was significantly lower than the low albumin group (50% versus 83.3% P=0.005)." (PMID 26644884, 2015). "Among the laboratory findings, anemia, lymphocytopenia, total protein, albumin,and C-reactive protein were significant." (PMID 26070207, 2015). "Albumin levels < 3.5 g/dl were increasingly more frequent across higher grades of anemia and lower CD4 counts." (PMID 26825478, 2015). "We performed the present longitudinal study to determine the relationship between baseline serum albumin and future anemia in hemodialysis patients." (PMID 26644884, 2015). "At admission, blood tests revealed leukocytosis, slight anemia, decreased albumin, and slightly elevated blood urea nitrogen." (PMID 26690238, 2015). "Eighteen out of 24 patients in the low albumin group and 35 out of 48 (72.9) patients in high albumin group had anemia (P=0.54)." (PMID 26644884, 2015). "The findings of this study indicate that low serum albumin in hemodialysis patients is a predictor of anemia indicating unresponsiveness to conventional treatment of anemia." (PMID 26644884, 2015). "A higher pulse pressure, LVMI, and serum uric acid and phosphorus levels were associated with anemia, whereas a lower BMI and lower levels of serum albumin, cholesterol, and calcium were related to anemia." (PMID 26430892, 2015). "The results of the present study found a relationship between low serum albumin and anemia, possibly due to hyporesponsiveness to ESA in hypoalbuminemic patients." (PMID 26644884, 2015). "In high serum albumin group however, the prevalence of anemia decreased significantly in the high serum albumin group (50% versus 83.3%, P=0.005)." (PMID 26644884, 2015). "We assessed the association of the urinary albumin-to-creatinine ratio (ACR) and eGFR with anemia in CKD patients." (PMID 26430892, 2015). "Risk factors for adverse reactions to antituberculosis drugs included age > 60 years, treatment regimens, alcoholism, anemia, and HIV co-infection, as well as sodium, iron, and albumin deficiency." (PMID 25750677, 2015). "Laboratory findings also show decreased coping capability of infected and indomethacin treated rats: higher white blood cell counts, increased neutrophil ratio, anaemia, decreased concentration of serum proteins (albumin, globulin, total protein) and CRP." (PMID 25001579, 2014). "A blood test showed anemia (a hemoglobin level of 6.1 g/dl), a low albumin level (2.4 g/dl), a high CRP level (13.59 mg/dl), a low platelets count (8.7×104/μl) and hyper gammaglobulinemia (2,993 mg/dl)." (PMID 24438824, 2014). "Blood tests revealed anemia (hemoglobin: 8.3 g/dl), thrombocytopenia (3.3×104/μ), a low albumin level (2.3 g/dl) and a high CRP level (10.75 mg/dl)." (PMID 24438824, 2014).
anemia (continued). "In emergency surgery, the fact that the patients received intra- and postoperative blood transfusions suggested that they had anemia, low total protein and albumin levels, or decreased concentrations of coagulation factors." (PMID 24445681, 2014). "Anemia (OR: 1.89, 95% CI: 3.11–1.14), lower concentrations of albumin (OR: 4.46, 95% CI: 2.52–7.86), and higher levels of log10 CRP (OR: 1.79, 95% CI: 1.20–2.65) were also associated with greater serum selenium deficiency." (PMID 25401501, 2014). "Laboratory studies are non-specific and have identified that patients with UELS exhibit low albumin, elevated lactic dehydrogenase, anemia and abnormal liver function." (PMID 25120671, 2014). "The studies included on NT-proBNP and albumin showed a high level of similarity (I2=0%), whereas the studies included on anemia, hs-CRP, and cardiac troponin T showed higher levels of dissimilarity (I2>50%)." (PMID 26557244, 2014). "There is only one reported case in the literature of a 15-month-old with collagenous gastroduodenocolitis who presented with profound diarrhea, anemia, and low albumin." (PMID 25221677, 2014). "After improvement in health status, anemia (9g/dL) and albumin concentration (37g/L), azathioprine (2,5mg/kg/day, total of 3 months of treatment) and IFX (induction regimen with 5mg/kg, weeks 0, 2 and 6) were prescribed with unchanged disease activity." (PMID 24396560, 2013). "Anaemia, nutrition (albumin, prealbumin), and inflammatory markers (CRP, thrombocytosis, and erythrocyte sedimentation rate) cannot be recommended for diagnostics of NSAID-induced enteropathy." (PMID 24382953, 2013). "Upregulation of proinflammatory cytokines leads to elevated levels of C- reactive protein (CRP) and albumin and chronic inflammation is also related to the development of anemia frequently referred as anemia of the chronic disease." (PMID 23294910, 2013). "Factors associated with indeterminate QFT results were HD (OR: 10.535 [1.336–83.093]), dialysis duration (OR: 1.113 [1.015–1.221] per year increment), anemia (OR: 8.760 [1.014–75.651]), and serum albumin level (OR: 0.244 [0.086–0.693] per 1 g/dL increment)." (PMID 22916137, 2012). "Patients receiving HD or long duration of dialysis, and those with anemia or lower albumin level are likely to have a QFT-indeterminate result." (PMID 22916137, 2012). "Of 1426 patients, 314 (17.6%) had anemia (≤10 g/dl), and of the 1178 patients with albumin data, 192 (10.7%) had low albumin levels (<3.5 g/dl)." (PMID 22985058, 2012). "Lymphopenia was found in 26 (61 %) patients, anemia in 13 (36 %), and low serum albumin level in 12 (33 %)." (PMID 22682004, 2012). "A majority of patients presented with anemia (58%), low serum albumin (70%), elevated CRP (> 10 mg/L; 59%)." (PMID 21406082, 2011). "Overall, 92 out of 109 (84%) participants had low serum albumin (≤36 g/L) and 43 out of 97 tested (44%) had anemia at baseline (hemoglobin ≤110 g/L)." (PMID 22254084, 2011). "The presence of anemia and low albumin was more pronounced in the classical group than the screening-detected group." (PMID 21245600, 2011). "According to univariete and multivariate Logstic regression analysis, age, clinical stage, PS score and albumin levels were closely related to pre-treatment cancer-related anemia." (PMID 20959070, 2010). "Majority of the patients presented anemia (65%), low albumin level (77.5%) and high CRP level (54%)." (PMID 20537187, 2010). "Cox multivariate regression analysis confirmed that anemia, clinical stage, PS score, albumin level were the independent prognostic factors in advanced NSCLC." (PMID 20959070, 2010). "Since 1994, this quality assurance effort has included collection of clinical parameters in the areas of anemia management, dialysis adequacy, and serum albumin." (PMID 18509683, 2009). "Risk factors for developing PR in HIV-negative patients are: anemia (Hb<6.8 mmol/l), low serum albumin (< 30 g/l) and a low lymphocyte count (< 0.8 × 109/l)." (PMID 20181173, 2009).
anemia (continued). "Donkey serum albumin significantly improves hematological function in mice with CP-induced anemia." (PMID 42064839, 2026). "Biochemical analysis revealed significantly lower serum iron, ferritin, transferrin saturation, albumin, and prealbumin levels among anemic girls, alongside elevated total iron-binding capacity and CRP, indicating a predominance of iron deficiency anemia with an inflammatory component." (PMID 42232018, 2026). "Therefore, during clinical treatment, it is necessary to maintain the patient’s serum albumin and lymphocytes at normal levels as much as possible, and prevent anemia to increase the ability to resist combined TB infection." (PMID 41551455, 2026). "The laboratory data showed anemia [91g/L (normal: 115–150g/L)], normal renal function with proteinuria, high serum lactic dehydrogenase [278 U/L, (normal: 120–250 U/L)], low serum albumin [28g/L, (normal: 40–55g/L)], abnormal erythrocyte sedimentation rate [25mm/H (normal: 0–20mm/H)]." (PMID 41357603, 2025). "Fourth, given our observation that intestinal bleeding–induced anemia may reduce albumin levels in active UC, a future study will quantify the extent of this relationship." (PMID 41586218, 2025). "Albumin, dry weight, anemia and mineral bone parameters remained stable in both groups." (PMID 41464753, 2025). "A nomogram model was constructed based on the identified risk factors, with the predicted probability calculated as P = ex / (1 + ex), where x = –3.619 + 1.678 × age + 1.224 × ISS stage + 1.102 × ECOG score + 1.227 × anemia + 1.322 × neutropenia + 1.087 × albumin level." (PMID 41232431, 2025). "Supportive care included platelet transfusions for counts <20 × 109/L, red blood cell transfusions for symptomatic anaemia, continuous insulin infusion to control hyperglycaemia (target fasting glucose <10 mmol/L), and intravenous albumin supplementation to maintain serum albumin >30 g/L." (PMID 41211059, 2025). "Considering that the HALP score consists of albumin levels reflecting nutritional and inflammatory status, hemoglobin levels showing anemia status, and lymphocyte and platelet levels showing inflammatory status, it seems to be appropriate for use in the emergency department for geriatric patients." (PMID 39838526, 2025). "Moreover, numerous factors such as ulcer size (diameter >5cm), low albumin, anemia, high HbA1c (>7.5%), high WBC levels, and ischemia have been confirmed to be associated with major amputations in DFU." (PMID 41384024, 2025). "Thus, the significant variables in the ASM were age (HR, 0.32; p = 0.004), mFI-5 (HR, 1.26; p = 0.005), TNM stage (HR, 2.96; p < 0.001), TOG (HR, 1.60; p = 0.010), anemia (HR, 1.79; p = 0.002), and serum albumin (HR, 0.38; p < 0.001)." (PMID 40572703, 2025). "Data on vitamin D, vitamin B12, iron, calcium, albumin levels, and anemia were extracted." (PMID 41193797, 2025). "In addition, higher ctDNA was associated with worse performance status/ECOG score of 2 + (P < 0.001), albumin below the lower limit of normal (P = 0.047), anemia (P = 0.012), elevation in ALK (P < 0.001), and higher NLR (P = 0.006)." (PMID 40445506, 2025). "Previous studies have identified several risk factors for the development of FN in patients receiving R-CHOP-21, including female sex, disease stage, international prognostic index (IPI), advanced age, poorer performance status, bone marrow involvement, anemia, and low baseline serum albumin." (PMID 40904615, 2025). "In addition, Human Albumin (20%) was injected from Day 60 to Day 67 to correct hyperproteinaemia, and Polysaccharide Iron Complex was orally administered to correct anaemia." (PMID 40308961, 2025). "For patients with RAR ≥ 7.18, it is recommended to intensify monitoring and initiate early intervention, such as optimizing nutritional support (e.g., albumin supplementation), controlling inflammatory responses (e.g., rational use of glucocorticoids), and correcting anemia." (PMID 40630492, 2025).